TMEM119 (transmembrane protein 119)
Diseases named in the same sentence as TMEM119 in open-access papers (continued):
Sharing a sentence is not in itself a finding about the gene and the disease.
osteosarcoma (9 papers, 2018 to 2025). A usually aggressive malignant bone-forming mesenchymal neoplasm, predominantly affecting adolescents and young adults. "On the other hand, in cancer overexpression of TMEM119 has been reported, specifically in osteosarcoma tissues, and has been associated with a poor prognosis." (PMID 37936608, 2023). "TMEM119 is up-regulated in osteosarcoma cells, and its overexpression is associated with increased tumor size, clinical stage, distant metastasis, and poor prognosis." (PMID 35687691, 2022). "TMEM119 (transmembrane protein 119) was observed to be highly upregulated in osteosarcoma derived samples as compared to healthy samples." (PMID 38966281, 2024). "Further research showed that Transmembrane protein 119 (TMEM119) promoted osteosarcoma cell proliferation, migration, and invasion via increasing the TGF‐β pathway‐related factors (BMP2, BMP7, and TGF‐β) expression." (PMID 36408691, 2023). "While U2OS and MG63 cells transfected with TMEM119 siRNA were treated with TGF-β or vehicle, exposure to TGF-β rescued the effects of TMEM119 siRNA and significantly promoted osteosarcoma cell migration and invasion." (PMID 37936608, 2023). "In recent years, more and more studies have revealed the involvement of TMEM119 in various cancers, including gastric cancer, osteosarcoma, and hepatocellular carcinoma." (PMID 33731124, 2021). "Study also found that TMEM119 promotes proliferation, migration and invasion of osteosarcoma cells partly through TGF-β/BMP signaling." (PMID 33731124, 2021). "In BALCL11 a copy number amplification (approximately 50 copies) was detected involving TMEM119, a recently characterised oncogene implicated in transforming growth factor beta (TGF-β) signalling in osteosarcoma." (PMID 30546832, 2018). "Moreover, the gene set enrichment analysis revealed that TMEM119 expression in osteosarcoma tissues is positively correlated with cell cycle, apoptosis, metastasis and TGF-β signaling." (PMID 38966281, 2024). "The presence of TMEM119 in osteosarcoma cells is related to cell invasion and migration, yet its function in microglia remains unknown." (PMID 31829283, 2019). "Similarly in osteosarcoma, TMEM119 was connected with tumor size, clinical stage and overall survival time, and associated with cell cycle, metastasis, apoptosis as well as TGF-β signaling in osteosarcoma cell lines." (PMID 37483484, 2023). "The reduction of the TMEM119 expression in U2OS and MG63 cells using small interfering RNA revealed that downregulation of TMEM119 could inhibit the proliferation of osteosarcoma cells by inducing cell cycle arrest in G0/G1 phase and apoptosis." (PMID 38966281, 2024).
ischemic stroke (7 papers, 2021 to 2024). A stroke disorder caused by obstruction of blood flow to the brain, due to thrombotic (local blood clot formation) or embolic (due to a blood clot or other material traveling from another site) event. "Tmem119 immunoreactivity was found to significantly decrease in mouse models of traumatic brain injury and ischemic stroke." (PMID 38308250, 2024). "We measured microglia TMEM119 immunofluorescence to assess if a portion of the IBA1-positive cells present in the ipsilateral brain regions after ischemic stroke were infiltrating macrophages." (PMID 33618737, 2021). "Our purpose was to identify microglial and macrophage populations regulated by ischemic stroke using morphology analysis and the presence of microglia transmembrane protein 119 (TMEM119)." (PMID 33618737, 2021). "The use of TMEM119 to distinguish between microglia and macrophage cell populations in preclinical models of adult ischemic stroke is limited." (PMID 33618737, 2021). "In light of these morphological and methodological incongruities, we are unable to definitively distinguish microglia from infiltrating macrophage cell populations in proximity to brain injury 24 h after ischemic stroke using TMEM119 alone." (PMID 33618737, 2021). "Our primary purpose was to utilize both morphological analysis and a combination of TMEM119 immunofluorescence and protein expression to distinguish between microglial and infiltrating macrophage populations after ischemic stroke and 24 h of reperfusion." (PMID 33618737, 2021). "Second, it is possible that TMEM119 possesses a functional response to a gross injury such as ischemic stroke." (PMID 33618737, 2021). "Combining two in situ methodologies, morphological analysis and TMEM119 immunofluorescence and protein expression, our purpose was to definitively identify microglial and macrophage populations regulated by ischemic stroke." (PMID 33618737, 2021). "The expression of Tmem119, however, decreased significantly in a time-dependent manner (% of relative intensity: 5.90 ± 3.99 at 6 h, 3.02 ± 2.97 at day 1, 1.44 ± 1.34 at day 3, 1.09 ± 1.41 at day 7) after ischemic stroke." (PMID 33409730, 2021). "However, one study reported that the change to microglia morphology was not congruent with loss of Tmem119 expression in a murine model of ischemic stroke." (PMID 38308250, 2024). "Our findings suggest that TMEM119 is not a stable microglia marker in male and female mice in the context of ischemic stroke." (PMID 33618737, 2021). "Instead, we suggest that in the context of acute ischemic stroke injury, TMEM119 is not a stable marker to denote microglia from infiltrating macrophages." (PMID 33618737, 2021). "However, in Tmem119-CreERT2; Nr4a1fl/fl mice, microglial NR4A1 was specifically knockout, enabling us to confirm the neuroprotective role of microglial NR4A1 in the context of ischemic stroke." (PMID 37486903, 2023). "They reported that Tmem119 presence was decreased in ramified microglia in a brain region proximal to the site of injury, thus, concluding that Tmem119 is not a stable microglia marker in the context of ischemic stroke." (PMID 35221925, 2022). "As shown by those antibodies, the number of Tmem119 and CX3CR1-double positive cells decreased significantly over time (% of Tmem119 + CX3CR1: 11.59 ± 3.75 at 6 h, 3.17 ± 0.50 at day 1, 2.47 ± 0.21 at day 3, 3.14 ± 0.59 at day 7) after ischemic stroke compared with the sham group (16.68 ± 0.27)." (PMID 33409730, 2021).
multiple sclerosis (7 papers, 2018 to 2023). A progressive autoimmune disorder affecting the central nervous system resulting in demyelination. "It is postulated that Tmem119+ microglia are downregulated in several models of neurodegenerative diseases, including multiple sclerosis." (PMID 37744880, 2023). "TMEM119 reliably stains microglia in the human brain, while macrophages (Iba1+/CD68+) at sites of necrotic lesion in human multiple sclerosis (MS) brains do not express TMEM119." (PMID 30241479, 2018).
ovarian carcinoma (7 papers, 2021 to 2025). A malignant neoplasm originating from the surface ovarian epithelium. "TMEM119 overexpression in ovarian cancer is associated with poorer prognosis and promotes cancer progression." (PMID 41465326, 2025). "TMEM119 was observed to be overexpressed in ovarian cancer (OV) tissues and associated with poor survival in OV patients." (PMID 37483484, 2023). "Therefore, the expression of TMEM119 was positively associated with proliferation, invasion and migration of ovarian cancer cells." (PMID 33731124, 2021). "Studies have shown that TMEM119 facilitates the proliferation, invasion, and migration of ovarian cancer cells, potentially through the PDGFRB/PI3K/AKT signaling pathway." (PMID 41465326, 2025). "The genes are associated with laryngeal cancer (MEOX2), cervical cancer (FGF7), oral cancer (DPT), breast cancer (CILP) or ovarian cancer (TMEM119) and LAMP3-positive dendritic cells are generally associated with cancer." (PMID 38671536, 2024). "PDGRFB was recently associated with TMEM119, another member of the UCEC triangle GRN, and AKT, a previously identified endometrial cancer hub gene, in ovarian cancer." (PMID 34791179, 2022). "In conclusion, the present study demonstrated that TMEM119 is overexpressed in ovarian cancer and promotes ovarian cancer progression." (PMID 33731124, 2021). "To investigate the functions of TMEM119 in ovarian cancer, we firstly examined the expression level and prognostic value of TMEM119 in various database." (PMID 33731124, 2021). "CCK-8 experiments demonstrated that over-expressed TMEM119 induced an increase in cell viability of ovarian cancer cells." (PMID 33731124, 2021). "High TMEM119 protein expression also induced poor survival in ovarian cancer patients in the Human Protein Atlas database." (PMID 33731124, 2021). "Our results revealed that TMEM119 promoted proliferation, invasion and migration of ovarian cancer cells in vitro." (PMID 33731124, 2021). "In GEPIA database, higher mRNA level of TMEM119 was detected in ovarian cancer tissues compared to that in normal ovarian tissues." (PMID 33731124, 2021). "To further explore the molecular mechanisms of TMEM119 involved in ovarian cancer progression, we combined datasets from TCGA and CCLE databases to investigate the pathways associated with TMEM119 in ovarian cancer." (PMID 33731124, 2021). "To further explore the effects of TMEM119 on the proliferation, invasion, and migration of ovarian cancer cells, we downregulated TMEM119 expression in OVCAR-3 and A2780 cells using RNA interference." (PMID 33731124, 2021). "In order to investigate the effect of TMEM119 on the malignant behavior of ovarian cancer cells, we respectively carried out functional experiments after knockdown and overexpression of TMEM119." (PMID 33731124, 2021). "Taken together, these findings suggested that TMEM119 can function an upstream of PDGFRB to regulate ovarian cancer progression." (PMID 33731124, 2021). "EdU experiments demonstrated that the proliferative ability of ovarian cancer cells decreased after knockdown of TMEM119." (PMID 33731124, 2021). "In the present study, we firstly reported the oncogenic roles for TMEM119 in ovarian cancer by detecting its clinical significance in ovarian cancer patients and exploring its influence on malignant behaviors of ovarian cancer cells." (PMID 33731124, 2021). "TMEM119 promoted proliferation, invasion and migration of ovarian cancer cells partially via upregulating PDGFRB." (PMID 33731124, 2021). "Fifty-four patients with epithelial ovarian cancer were divided into high TMEM119-expression group and low TMEM119-expression group with the median protein expression level as the cutoff value." (PMID 33731124, 2021). "TMEM119 can regulate proliferation, invasion, and migration in ovarian cancer cells via the PDGFRB/PI3K/AKT signaling pathway." (PMID 33731124, 2021). "Our study demonstrated that PI3K/AKT signaling could be activated by TMEM119 in ovarian cancer cells." (PMID 33731124, 2021).
ovarian carcinoma (continued). "Furthermore, we explored the expression of TMEM119 protein in 54 primary epithelial ovarian cancer specimen and 19 pseudonormal ovarian tissues via Western blot and observed higher TMEM119 protein levels in cancer tissues." (PMID 33731124, 2021). "However, the function of TMEM119 in ovarian cancer is still unclear." (PMID 33731124, 2021). "However, after including known variables associated with prognosis, TMEM119 expression level did not turn out to be an independent prognostic factor in ovarian cancer." (PMID 33731124, 2021). "Therefore, it still requires further exploration to figure out whether TMEM119 upregulates the transcription of PDGFRB in ovarian cancer by interacting directly with transcription factors and by binding with ligands to transfer signal into the cytoplasm or by other potential mechanisms." (PMID 33731124, 2021). "Therefore, TMEM119 could be a gene involved in ovarian cancer progression." (PMID 33731124, 2021). "Recently, TMEM119 was reported to be overexpressed in ovarian cancer tissues, and expression levels are positively related to the International Federation of Gynecology and Obstetrics (FIGO) stages, suggesting that TMEM119 might be a prognostic biomarker." (PMID 37936608, 2023). "Consistently, we observed positive expression of TMEM119 in ovarian cancer tissue and negative expression in normal ovarian tissue in the Human Protein Atlas database." (PMID 33731124, 2021). "In order to further detect the relationship between TMEM119 and PDGFRB in ovarian cancer progression, we downregulated PDGFRB expression by RNA interference and found there was no significant change in both mRNA and protein expression level of TMEM119." (PMID 33731124, 2021). "To further understand the molecular mechanisms of TMEM119 in progression of ovarian cancer, we conducted GSEA analyses in the transcriptomic data of OV patients from the TCGA database and in the transcriptomic data of 44 ovarian cancer cell lines from the CCLE project, respectively." (PMID 33731124, 2021).
amyotrophic lateral sclerosis (6 papers, 2018 to 2026). Amyotrophic lateral sclerosis (ALS) is a neurodegenerative disease characterized by progressive muscular paralysis reflecting degeneration of motor neurons in the primary motor cortex, corticospinal tracts, brainstem and spinal cord. "A significant increase in the density of TMEM119‐positive cells has been observed in the motor cortex and subcortical white matter of patients with amyotrophic lateral sclerosis (ALS) compared to controls." (PMID 41488805, 2026). "Similarly, in the model of amyotrophic lateral sclerosis (ALS) - mSOD1, microglia showed a reduction of the core microglial genes Tmem119 and P2ry12 and upregulated Trem2, Tyrobp, Lpl, and Cst." (PMID 33809675, 2021). "It was shown that microglia uniformly downregulate their homeostatic signature genes, such as Sall1, Pu.1, Tmem119, Cx3cr1, and P2ry12/13 and upregulate risk genes for AD, such as Apoe and Trem2, in mouse models for aging, AD (5XFAD and APP-PS1), and amyotrophic lateral sclerosis (ALS) (SOD1)." (PMID 30108586, 2018).
breast carcinoma (6 papers, 2022 to 2025). "Lastly, we employed a syngeneic mouse model of breast cancer brain metastasis (E0771-BrM) to investigate Tmem119 expression in tumor-associated microglia." (PMID 38308250, 2024). "A recent study showed that TMEM119 was highly expressed in an α-SMAhigh cluster in breast cancer-associated fibroblasts; moreover, an α-SMAhigh cluster produced several growth factors involved in cancer development and progression." (PMID 37537159, 2023). "Finally, we used a murine model of breast cancer brain metastasis (E0771-BrM) to assess the reliability of Tmem119 as a marker to distinguish tumor-associated microglia from peripheral myeloid cells." (PMID 38308250, 2024). "We used an LPS and breast cancer brain metastasis model to show a reduction in Tmem119 gene and protein expression after pathological activation." (PMID 38308250, 2024). "One of the members, TMEM119, has been reported to promote the stemness of breast cancer and is negatively correlated with the survival of patients." (PMID 36142451, 2022). "It was shown that β-catenin and TMEM119 have positive feedback as β-catenin has 3 binding sites to the TMEM119 promoter, upregulating the expression of TMEM119 in breast cancer cells, and in consequence, TMEM119 promotes pluripotency of breast cancer cells in a β-catenin dependent manner." (PMID 37936608, 2023). "In addition, the EMT process was favored by the overexpression of TMEM119, while in the knockdown cells, this process was inhibited, demonstrated by the expression level of the EMT markers vimentin and E-cadherin, these data reveal that TMEM119 promotes pluripotency in cells of breast cancer." (PMID 37936608, 2023). "In addition, TMEM119 can activate the Wnt/β-catenin pathway in breast cancer cells." (PMID 37936608, 2023).
amyloid (5 papers, 2018 to 2022). "In the APP/PS1 model with only amyloid pathology, TMEM119 levels significantly increased with the repopulation of microglia in males but not in females." (PMID 35787714, 2022). "TREM2 was correlated with Iba1, TMEM119, and CD68, consistent with TREM2 upregulation in specific phenotypes of disease or amyloid-associated microglia." (PMID 33178186, 2020). "Moreover, GFP+ cells in the brain parenchyma do not express Tmem119, a microglia-enriched transcript that is detectable in APP/PS1 brains but downregulated in the 5XFAD model of accelerated amyloid pathogenesis." (PMID 35511433, 2022).
ischemia (5 papers, 2020 to 2024). A hypoperfusion of the BLOOD through an organ or tissue caused by a PATHOLOGIC CONSTRICTION or obstruction of its BLOOD VESSELS, or an absence of BLOOD CIRCULATION. "We observed an up-regulation of the CD68-positive microglia sub-population and a down-regulation of the TMEM119-positive microglia sub-population after ischemia which is in line with numerous other studies investigating microglial cell activation after brain lesions." (PMID 39272984, 2024). "Although TMEM119 distinguishes microglia and peripheral macrophages under homeostatic conditions, following ischemia infiltrating peripheral macrophages infiltrating take on a “microglia-like” state and become virtually indistinguishable from resident microglia proliferating locally." (PMID 36721258, 2023). "Interestingly, a significantly higher Tmem119 expression was observed in the ischemia group at the two late time points, 3 and 7 days." (PMID 32833183, 2021). "Remarkably, ischemia-associated microglia (amoeboid-like CXCL10+ cells lacking P2RY12 and TMEM119 protein expression) filled the lesion core." (PMID 32573436, 2020).
Obesity (5 papers, 2020 to 2024). Accumulation of substantial excess body fat. "Here, using a model of microglia derived from UCBMC in vitro (iMGL), we report an increase in the expression of activation markers (CD163, CX3CR1, TMEM119, HLA-DR) with pregravid obesity, while phagocytic capacity was reduced." (PMID 39872537, 2024). "Induced UCB-derived microglia-like cells (iMGL) expressed higher levels of activation markers CD163, CX3CR1, TMEM119, and HLA-DR but reduced phagocytic capacity with maternal pregravid obesity." (PMID 39872537, 2024). "Therefore, Tmem119 and Ptprk may play important roles in the development of obesity and diabetes." (PMID 34691555, 2021). "To examine whether early obesity promotes Th2 cytokine signaling in microglia, we quantified IL4Ra and interleukin-10 receptor-alpha (IL10Ra) expression in CD45LO/Ly6CLO/CD169−/TMEM119+ microglia." (PMID 34330904, 2021).
gastric cancer (4 papers, 2021 to 2025). A primary or metastatic malignant neoplasm involving the stomach. "TMEM119 has been reported by previous study to enhance gastric cancer cell migration and invasion by activating STAT3 signaling pathway." (PMID 33731124, 2021). "Clinical gastric cancer tissues exhibited increased TMEM119 expression." (PMID 40219804, 2025). "Furthermore, a decrease in the expression of TMEM119 in gastric cancer cell line SGC-7901 reduced cell viability, favoring apoptosis." (PMID 37936608, 2023). "TMEM119, also known as Osteoblast Induction Factor (OBIF), plays important role in bone formation and normal bone mineralization and its overexpression enhances viability, invasion and migration of gastric cancer cells." (PMID 33731124, 2021).